ANKRD52 (ankyrin repeat domain 52)
Description:
Putative regulatory subunit of protein phosphatase 6 (PP6) that may be involved in the recognition of phosphoprotein substrates.
Synonyms: PP6-ARS-C; FLJ34236; ARSC
Tractability: PROTAC: ubiquitination databases record sites on it.
Target class: Protein phosphatase regulatory subunit; Phosphatase; Enzyme; Protein Phosphatase
Gene: Protein-coding gene on chromosome 12 (56,237,807 to 56,258,384, reverse strand). Ensembl gene ENSG00000139645.
Subcellular location (Human Protein Atlas): Mitochondria; Nucleoplasm
Gene Ontology:
Molecular function: protein binding
Genetic constraint (gnomAD): Loss-of-function variants: 7 observed, 107.99 expected, observed/expected ratio (o/e) 0.0648, 90% interval 0.036 to 0.12. The upper end of that interval is the gene's LOEUF score, 0.12, which puts it in group 1 of 6, group 1 being the genes least tolerant of losing a copy. Missense variants: 839 observed, 1,364.5 expected, observed/expected ratio (o/e) 0.61, 90% interval 0.58 to 0.65. Synonymous variants: 528 observed, 556.62 expected, observed/expected ratio (o/e) 0.95, 90% interval 0.88 to 1.02.
Homologues: Orthologues: chimpanzee ANKRD52 (99% identical), macaque ANKRD52 (99% identical), guinea pig ANKRD52 (99% identical), dog ANKRD52 (99% identical), pig ANKRD52 (99% identical), rat Ankrd52 (99% identical), mouse Ankrd52 (99% identical), rabbit ANKRD52 (99% identical), tropical clawed frog ankrd52 (80% identical), zebrafish ankrd52a (67% identical). Paralogues in human: ANKRD28 (59% identical), ANKRD44 (57% identical), ANKRD55 (15% identical).
Diseases named in the same sentence as ANKRD52 in open-access papers:
ANKRD52 is named in the same sentence as 11 diseases in open-access papers, as found by Europe PMC text mining. Sharing a sentence is not in itself a finding about the gene and the disease. The quoted sentences say what the papers report.
melanoma (2 papers, 2021 to 2025). A malignant, usually aggressive tumor composed of atypical, neoplastic melanocytes. "We herein identified another novel hsa_circ_0026926 derived from ANKRD52 and found that circANKRD52 (hsa_circ_0026926) promoted the growth and angiogenesis of melanoma cells by sponging miR‐141‐3p and might provide a potential biomarker for melanoma." (PMID 41173801, 2025). "Like ANKRD52, which is mutated in 4.8% colorectal adenocarcinoma and 1.5% of all cancer types, PPP6C harbors recurrent and potentially driver mutations, such as the R264C mutation in 3% melanoma, which may disrupt PPP6C binding to ANKRD52 and thus the enzymatic activity." (PMID 34853298, 2021).
breast carcinoma (1 paper, 2021). "The results suggested that metastasis associated RNAs, including AHRR, TTC34, CNTRL, ANKRD52, BCAR1, TMEM151B, PANX2, hsa-miR-105-5p, hsa-miR-4435, hsa-miR-5691, hsa-miR-92a-1-5p, and LINC01742 could serve as the prognostic biomarkers of breast cancer patients." (PMID 34055638, 2021). "Inversely, breast cancer patients with higher expression level of AHRR, ANKRD52, BCAR1, PANX2, hsa-miR-105-5p, hsa-miR-4435, and LINC01742 showed the lower OS." (PMID 34055638, 2021).
colorectal adenocarcinoma (1 paper, 2021). The most common type of colorectal carcinoma. "Given a 4.8% prevalence of ANKRD52 mutations (19/399) in colorectal adenocarcinoma and 1.5% (153/10182) in all cancer types, our studies suggest that these patients might not benefit as much from T cell-based immunotherapies." (PMID 34853298, 2021).
hepatocellular carcinoma (1 paper, 2019). A malignant tumor that arises from hepatocytes. "While the roles of Ankrd52 and Clcn5 in liver disease remain unclear, Peg10 has been widely studied in hepatocellular carcinoma (HCC) pathology." (PMID 31470644, 2019).
influenza (1 paper, 2013). An acute viral infection of the respiratory tract, occurring in isolated cases, in epidemics, or in pandemics; it is caused by serologically different strains of viruses (influenzaviruses) designated A, B, and C, has a 3-day incubation period, and usually lasts for 3 to 10 days. "Quantitation of their expression in influenza infected A549 cells showed that ANKRD52, ATP5A1, FOXN3 were downregulated whereas all the other transcripts were upregulated." (PMID 24116168, 2013).
lung adenocarcinoma (1 paper, 2023). A carcinoma that arises from the lung and is characterized by the presence of malignant glandular epithelial cells. "ANKRD52 is reported to function as a tumor metastasis suppressor in lung adenocarcinoma." (PMID 37521466, 2023).
tumor (4 papers, 2021 to 2024). "Like Jak1/2 and B2m, Ankrd52 sgRNAs exhibited time-dependent enrichment in tumor cells in the presence of T cells, providing direct evidence that loss of ANKRD52 conferred resistance to T cell killing." (PMID 34853298, 2021). "Additionally, ANKRD52 was found as a suppressor of tumor metastases, and reduced ANKRD52 levels are associated with late-stage lung cancer." (PMID 34853298, 2021). "ANKRD52 is a tumor suppressor that regulates PP6c-mediated PAK1 dephosphorylation, which inhibits proliferation." (PMID 38338859, 2024). "Although alterations of several genes (such as Hebp1, Eno1, and Taf9) other than Ankrd52 are more frequently detected in our tumor profiling, their targeting sgRNAs exhibited much less enrichment or fold-change as compared to those of Ankrd52." (PMID 34853298, 2021). "In addition to being a member of the PP6 holoenzyme, ANKRD52 inhibits tumor progression through PP6c-mediated dephosphorylation of PAK1." (PMID 37521466, 2023). "Loss of ANKRD52 caused a remarkable downregulation in the expression of IFNγ and IFNα responsive gene sets after MC38 cells were stimulated with IFNγ, a T cell cytokine essential for tumor immunity." (PMID 34853298, 2021). "Analysis of several published datasets on cancer patients receiving immunotherapies revealed a higher ANKRD52 mutation rate in tumor samples from non-responders than responders." (PMID 34853298, 2021). "Exhausted T cells (LAG3+ PD1+ or TIM3+ PD1+) were also decreased, possibly explaining why Ankrd52 mutation was not eliminated by PD-1 blockade in our tumor mutation profiling." (PMID 34853298, 2021). "The results of ANKRD52 level expressed that the HOXC10, KNOP1, and TRIM45 in the tumor tissue were higher in the paracancerous tissue, and the opposite was true for SGPP1." (PMID 37521466, 2023). "Furthermore, we found that 6–8 out of 10 sgRNAs targeting Ankrd52 were significantly enriched in WT and immunotherapy tumors compared to T cell-depleted tumors, suggesting that inactivation of ANKRD52 conferred a selective advantage for tumor cells against PD-1 independent T cell-mediated immunity." (PMID 34853298, 2021). "Tumor-infiltrating lymphocyte (TIL) analysis revealed that the proportions, but not activation or cytotoxicity, of CD4+ and CD8+ T cells were significantly decreased in Ankrd52-null tumors." (PMID 34853298, 2021).
cancer (1 paper, 2021). A tumor composed of atypical neoplastic, often pleomorphic cells that invade other tissues. "However, the growth disadvantage of Ankrd52-null tumors was abolished when implanted to WT mice, suggesting that loss of ANKRD52 enabled cancer cells to escape T cell immunity in vivo, thereby offsetting their intrinsic growth deficiency." (PMID 34853298, 2021). "SOCS1 suppresses JAK-STAT signaling and cancer immunotherapy, and its mRNA levels were reciprocally controlled by ANKRD52 and CK1α." (PMID 34853298, 2021). "Putting together, CRISPR library screens in vitro and in vivo demonstrate a direct role of ANKRD52 in modulating cancer sensitivity to T cell-mediated clearance." (PMID 34853298, 2021). "Taken together, these results indicate that ANKRD52 regulates cancer immunity mainly through miR-155-mediated silencing of SOCS1." (PMID 34853298, 2021). "Accordingly, significant decrease in total surface MHC-I was observed in both Ankrd52-null MC38 cancer cells isolated from tumors or cultured with IFNγ stimulation." (PMID 34853298, 2021). "We next sought to determine how ANKRD52 alters cancer cell’s interaction with T cell by comparing the transcriptome of Ankrd52-null cells with control cells." (PMID 34853298, 2021). "Genetic inactivation of the machinery or re-introduction of ANKRD52 frequent patient mutations dampens the JAK-STAT-interferon-γ signaling and antigen presentation in cancer cells, largely by abolishing miR-155-targeted silencing of suppressor of cytokine signaling 1 (SOCS1)." (PMID 34853298, 2021). "Like ANKRD52, transcript levels of these core miRNA processors negatively correlate with the SOCS1 level in a large number of human cancer types." (PMID 34853298, 2021). "Here the authors show that inactivation of proteins involved in microRNA-mediated gene silencing, such as ANKRD52 or AGO2, confers resistance to T cell-mediated immune response in a preclinical cancer model." (PMID 34853298, 2021).
ANKRD52 also shares sentences with these, for which no sentence is quoted: bladder cancers (1 paper); colorectal carcinoma (1); liver disease (1).